ADAMTS9 (ADAM metallopeptidase with thrombospondin type 1 motif 9)
Description:
Cleaves the large aggregating proteoglycans, aggrecan (at the '1838-Glu-|-Ala-1839' site) and versican (at the '1428-Glu-|-Ala-1429' site). Has a protease-independent function in promoting the transport from the endoplasmic reticulum to the Golgi apparatus of a variety of secretory cargos.
Synonyms: KIAA1312
Tractability: Antibody: UniProt places it where antibodies can reach, with high confidence; its Gene Ontology location is reachable by antibodies, with high confidence; UniProt predicts a signal peptide or a membrane-spanning region.
Gene: Protein-coding gene on chromosome 3 (64,515,654 to 64,688,000, reverse strand). Ensembl gene ENSG00000163638.
Subcellular location: Secreted, extracellular space, extracellular matrix; Endoplasmic reticulum
Subcellular location (Human Protein Atlas): Endoplasmic reticulum; Vesicles; Predicted to be secreted
Pathways (Reactome):
Disease: Defective B3GALTL causes PpS
Extracellular matrix organization: Degradation of the extracellular matrix
Metabolism of proteins: O-glycosylation of TSR domain-containing proteins
Gene Ontology:
Molecular function: metalloendopeptidase activity; metallopeptidase activity; endopeptidase activity; zinc ion binding
Biological process: cilium assembly; proteolysis; aorta morphogenesis; endothelial cell-matrix adhesion; extracellular matrix organization; heart valve morphogenesis; negative regulation of endothelial cell migration; negative regulation of sprouting angiogenesis; ventricular cardiac muscle tissue development; pigment cell development
Cellular component: endoplasmic reticulum; extracellular matrix; peri-centrosomal recycling endosome; cell surface; extracellular region
Genetic constraint (gnomAD): Loss-of-function variants: 104 observed, 260.87 expected, observed/expected ratio (o/e) 0.4, 90% interval 0.34 to 0.47. The upper end of that interval is the gene's LOEUF score, 0.47, which puts it in group 2 of 6, group 1 being the genes least tolerant of losing a copy. Missense variants: 2,328 observed, 2,538.9 expected, observed/expected ratio (o/e) 0.92, 90% interval 0.88 to 0.95. Synonymous variants: 975 observed, 909.27 expected, observed/expected ratio (o/e) 1.07, 90% interval 1.02 to 1.13.
Gene-disease validity (ClinGen):
ClinGen rates the evidence that ADAMTS9 causes each of these diseases.
ciliopathy (autosomal recessive): Limited. A genetic disorder of the cellular cilia or the cilia anchoring structures, the basal bodies, or of ciliary function.
Homologues: Orthologues: chimpanzee ADAMTS9 (99% identical), macaque ADAMTS9 (99% identical), pig ADAMTS9 (93% identical), dog ADAMTS9 (93% identical), rabbit ADAMTS9 (91% identical), mouse Adamts9 (89% identical), rat Adamts9 (88% identical), guinea pig ADAMTS9 (86% identical), tropical clawed frog adamts9 (71% identical), zebrafish adamts9 (50% identical). Paralogues in human: ADAMTS20 (50% identical), ADAMTS7 (23% identical), ADAMTS12 (22% identical), ADAMTS15 (21% identical), ADAMTS6 (20% identical), ADAMTS16 (20% identical), ADAMTS1 (20% identical), ADAMTS18 (20% identical), ADAMTS10 (19% identical), ADAMTS8 (19% identical), ADAMTS2 (18% identical), ADAMTS3 (18% identical), and 13 more.
Diseases named in the same sentence as ADAMTS9 in open-access papers:
ADAMTS9 is named in the same sentence as 97 diseases in open-access papers, as found by Europe PMC text mining. Sharing a sentence is not in itself a finding about the gene and the disease. The quoted sentences say what the papers report.
gastric cancer (18 papers, 2012 to 2026). A primary or metastatic malignant neoplasm involving the stomach. "This association has also been demonstrated for ADAMTS9 in gastric cancer, breast cancer, and multiple myeloma cells." (PMID 39940703, 2025). "What is more, in patients with gastric cancer, higher ADAMTS9 methylation was significantly associated with shortened survival, indicating its value as a prognostic factor." (PMID 39940703, 2025). "ADAMTS9 exerts an antitumor effect by inhibiting the phosphoinositide 3-kinase/protein kinase B/mammalian target of rapamycin (PI3K/AKT/mTOR) pathway in gastric cancer." (PMID 41517663, 2026). "For the ADAMTS9 gene, it was shown that it acts as a tumor suppressor in gastric cancer through AKT/mTOR signaling inhibition." (PMID 39940703, 2025). "ADAMTS9 can induce notable inactivation of the PI3K/AKT signaling pathway in gastric cancer cells by inhibiting its phosphorylation." (PMID 39678510, 2024). "RNF180 ubiquitinates DNMT3A, markedly reducing ADAMTS9 methylation levels and increasing its expression in gastric cancer." (PMID 39048965, 2024). "ADAMTS9 is a novel cancer regulator that has been reported to be involved in a variety of cancers, such as gastric cancer, liver cancer, breast cancer, prostate cancer, and bladder cancer." (PMID 37872487, 2023). "For instance, METTL3 facilitated angiogenesis and carcinogenesis by m6A-mediated ADAMTS9 suppression in gastric cancer." (PMID 36476503, 2022). "ADAMTS9 has been identified as a cancer-suppressor gene in gastric cancer and nasopharyngeal carcinoma." (PMID 33063817, 2020). "ADAMTS-9 acts as a functional tumor suppressor in gastric cancer through inhibiting the oncogenic AKT/mammalian target of rapamycin (mTOR) signaling pathway and ADAMTS-9 is related to beta cell function in type 2 diabetes." (PMID 29393911, 2018). "Another important tumour suppressor gene, ADAMTS9, was found to be frequently silenced in gastric cancer samples thereby making it an important prognostic marker." (PMID 28144288, 2017). "ADAMTS9 was reduced by promoter methylation in gastric cancer cells, and ADAMTS15 was genetically inactivated in colon cancer." (PMID 28503860, 2017). "A similar study revealed the RNF180/DNMT3A/ADAMTS9 axis in gastric cancer." (PMID 39048965, 2024). "In this study, we investigated the inhibitory effects of ADAMTS9 on gastric cancer (GC) cells." (PMID 33931579, 2021). "Of note, it has been indicated that the ADAMTS9 might execute its suppressive function in gastric cancer by repressing AKT/mTOR pathway." (PMID 33063817, 2020). "Mechanistically, ADAMTS9 was shown to inhibit the oncogenic Akt/mTOR/HIF1α signaling pathway that results in reduced proliferation, induction of apoptosis and inhibition of angiogenesis in gastric cancer." (PMID 24213506, 2012). "Hypermethylation of ADAMTS9 also correlated with poor survival of gastric cancer patients." (PMID 24213506, 2012). "METTL3 induced proliferation, migration, angiogenesis and tumorigenesis via inhibition of ADAMTS9 and modification of YAP1 and KLF2 in gastric cancer." (PMID 36003776, 2022). "However, the presence of Mettl3 diminishes the stability of ADAMTS9 mRNA through an m6A-YTHDF2-dependent pathway, consequently promoting angiogenesis and carcinogenesis in gastric cancer." (PMID 41517663, 2026). "No such differences in ADAMTS9 methylation in relation to tumor stage were observed in multiple myeloma, gastric cancer, or breast cancer." (PMID 39940703, 2025). "In addition, several studies have revealed that the ADAMTS9 and ADAMTS18 gene promoters are also hypermethylated in gastric carcinoma." (PMID 25936341, 2015).
type 2 diabetes (18 papers, 2008 to 2025). "ADAMTS16 has not been associated with any glycaemic traits in GWASs; however, a SNP in ADAMTS9 has been shown to be associated with increased type 2 diabetes risk, suggesting that ADAMTS gene family members contribute to diabetes pathophysiology." (PMID 40025146, 2025). "ADAMTS9 is a risk gene for type 2 diabetes development and its over-expression is associated with impaired insulin signaling in peripheral tissues and also with insulin resistance." (PMID 32316129, 2020). "ADAMTS9 has been shown to be associated with body fat distribution and other anthropometry/metabolic traits including type 2 diabetes, as well as age-related macular degeneration and other traits." (PMID 28100790, 2017). "In humans, an ADAMTS9 gene variant is associated with type 2 diabetes (T2DM) is most frequently linked with aging, cognitive impairment, AD-associated neuronal APP-Aβ deposits." (PMID 28373841, 2017). "It has been reported that insulin secretion is reduced by a variant of ADAMTS9 that confers increased type 2 diabetes risks in humans." (PMID 26218657, 2015). "Because a variant of ADAMTS9 has been established as a risk factor for type 2 diabetes, we investigated how ADAMTS9/GON-1 is involved in the insulin/IGF-like signaling pathway." (PMID 26218657, 2015). "It was reported that an ADAMTS9 gene variant found in the 5'-upstream region (rs4607103) is associated with type 2 diabetes." (PMID 26218657, 2015). "The ADAMTS9 gene has been associated to Type 2 Diabetes in a meta-analysis of genome-wide association data." (PMID 25071839, 2014). "Like type 2 diabetes-associated ADAMTS9 rs4607103, BMI-associated NEGR1 rs2815752 was associated with the phenotype-class of “Ever Smoked” in European Americans." (PMID 23382687, 2013). "In addition to its role in tumor suppression, ADAMTS9 has also been implicated in several age-related conditions including arthritis, type 2 diabetes, age-related macular degeneration and menopause." (PMID 28244876, 2017). "It has been reported that an ADAMTS9 gene variant is associated with type 2 diabetes." (PMID 26218657, 2015). "It has been reported that a variant of ADAMTS9 is associated with type 2 diabetes." (PMID 26218657, 2015). "We identified fourteen type 2 diabetes-associated genes discovered by the first waves of GWAS for which there was little prior evidence of their potential role in diabetes (Adam30, Adamts9, Camk1d, Cdc123, Cdkal1, Cdkn2a, Cdkn2b, Ext2, Hhex, Ide, Jazf1, Lgr5, Thada and Tspan8)." (PMID 23442068, 2013). "The major C-risk allele of rs4607103 near ADAMTS9, conferring increased risk of type 2 diabetes, associated with increased fasting plasma glucose levels (p = 0.007) and a reduced insulin-stimulated glucose uptake during a euglycemic-hyperinsulinemic clamp (p = 0.002)." (PMID 19789630, 2009). "ADAMTS9 is a metalloproteinase involved in thrombosis and angiogenesis and has been associated with cardiometabolic traits (waist-to-hip ratio, waist circumference, and type 2 diabetes) in GWAS, and with coronary artery calcification in a gene-by-smoking interaction GWAS17,18." (PMID 30510157, 2018). "And meta-analysis on three Caucasian GWAS yielded six additional loci (JAZF1, TSPAN8-LGR5, THADA, ADAMTS9, NOTCH2-ADAM30 and CDC123-CAMK1D) associated with type 2 diabetes at genome-wide statistic significance." (PMID 19862325, 2009). "A very recently published study investigated associations of the type 2 diabetes risk alleles in JAZF1, CDC123/CAMK1D, TSPAN8/LGR5, THADA, ADAMTS9, and NOTCH2 with obesity, insulin sensitivity, and insulin secretion in 4516 Danes." (PMID 18714373, 2008). "After determination of the risk alleles for these associations, only the risk allele of the ADAMTS9 SNP rs4607103 and the risk allele of the VEGFA SNP rs9472138 were identical with the recently reported risk alleles for type 2 diabetes." (PMID 18714373, 2008).
type 2 diabetes (continued). "Furthermore, a meta-analysis of three GWASs detected six novel variants (in JAZF1, CDC123/CAMK1D, TSPAN8/LGR5, THADA, ADAMTS9, and NOTCH2) that were associated with type 2 diabetes." (PMID 20161779, 2010). "However, it is not unexpected that our study was unable to find significant associations between SNPs in JAZF1, CDC123/CAMK1D, TSPAN8/LGR5 and ADAMTS9 and type 2 diabetes, since the meta-analysis required more than 9000 samples for an 80% power." (PMID 20161779, 2010). "Thus, our findings suggest that rs4607103 near ADAMTS9 may after PPARG Pro12Ala be the second gene locus conferring risk of type 2 diabetes due to insulin resistance." (PMID 19789630, 2009). "We conclude that the GON domain is critical for ADAMTS9/GON-1 function across species, which should help the understanding of type 2 diabetes in humans." (PMID 26218657, 2015). "The seven loci shed new light on regions containing genes with a reported role for type 2 diabetes (PPARG, ADAMTS9, VEGFA), lipids (GRB14, MAP3K1) and hormone metabolism (HSD17B4)." (PMID 23754948, 2013).
age-related macular degeneration (8 papers, 2016 to 2023). Age-related loss of vision in the central portion of the retina (macula), secondary to retinal degeneration. "In this context, genome-wide association studies have associated the ADAMTS9 locus with age-related macular degeneration, a major cause of adult-onset blindness, where RPE cell death and dysregulated angiogenesis are prominent features." (PMID 37169079, 2023). "The ADAMTS9 rs6795735 SNP was also associated with age-related macular degeneration, which typically occurs in older individuals, in a genome-wide association study." (PMID 28225792, 2017). "In eyes at high risk of age-related macular degeneration, one study identified lower ADAMTS9 mRNA levels, which could lead to higher MT1-MMP activity, and thus greater pro-MMP2 activation, together promoting retinal angiogenesis." (PMID 37169079, 2023). "ADAMTS genes (ADAMTS1, ADAMTS6 and ADAMTS9) may associate with age-related macular degeneration and MAP1B was higher expression in the macula of human eye." (PMID 37389979, 2023). "The functional link between ADAMTS9 and B3GLCT established here also provides credence to their recently reported association with age-related macular degeneration." (PMID 27687499, 2016). "A GWAS study on more than 17,100 patients, with advanced age-related macular degeneration (AMD) and over 60,000 controls, showed a significant association between AMD and loci in B3GLCT and ADAMTS9." (PMID 31795264, 2019). "Future functional analysis of ADAMTS9 and B3GLCT in age-related macular degeneration is thus warranted." (PMID 27687499, 2016).
breast carcinoma (7 papers, 2017 to 2025). "ADAMTS9 is poorly expressed in breast cancer, colorectal cancer, and GC and is associated with the hypermethylation of their promoters." (PMID 32884571, 2020). "The results confirmed that hypermethylation of CGI is associated with low ADAMTS9 expression in breast carcinoma." (PMID 29193730, 2018). "Demethylation treatment significantly restored ADAMTS9 expression, indicating promoter methylation could be the main mechanism underlying ADAMTS9 inactivation in breast cancer." (PMID 29193730, 2018). "We investigated the hypothesis that promoter methylation plays the vital role in ADAMTS9 expression regulation, which underlies a major mechanism for breast cancer development and progression." (PMID 29193730, 2018). "Our results suggest that ADAMTS9 is a TSG epigenetically inactivated in breast cancer, which functions through blocking EGFR‐ and TGFβ1/TβR(I/II)‐activated AKT signaling." (PMID 29193730, 2018). "Consistent with reports in other cancer types 14, we found ADAMTS9 inhibits the AKT/mTOR signalling pathway in breast cancer cells." (PMID 29193730, 2018). "The results showed that the CGI methylation of ADAMTS9 in breast cancer tissue was much higher than that in paired margin tissue and normal breast tissue." (PMID 29193730, 2018). "In this report, ADAMTS9 expression and methylation was analysed in breast cancer cell lines and tissue samples." (PMID 29193730, 2018). "In conclusion, we provide evidence suggesting ADAMTS9 as a novel tumour suppressor gene that is silenced by promotor hypermethylation in breast cancer." (PMID 29193730, 2018). "Consistently, ADAMTS9 was highly expressed in normal human mammary epithelial cell lines (HMEpC), but greatly reduced or completely silenced in multiple breast carcinoma cell lines (6/8, 75%)." (PMID 29193730, 2018). "ADAMTS9 RNA was significantly down‐regulated in breast cancer cell lines (6/8)." (PMID 29193730, 2018). "Accordingly, we speculated that ADAMTS9 inhibits carcinogenesis in breast cancer, at least in part, through blocking angiogenesis." (PMID 29193730, 2018). "Whether ADAMTS9 suppresses breast cancer angiogenesis involving HIF1α suppression deserves further studies." (PMID 29193730, 2018). "Next, we performed the cell invasion assay to investigate whether ADAMTS9 suppresses breast cancer cell invasion using transwell cell invasion assays." (PMID 29193730, 2018). "In addition, we demonstrated, for the first time, that ADAMTS9 inhibits AKT signaling, through suppressing its upstream activators EGFR and TGFβ1/TβR(I/II) in breast cancer cells." (PMID 29193730, 2018). "Furthermore, ADAMTS9 inhibits the AKT pathway through suppressing EGFR and TGFβ1/TβR(I/II) in breast cancer cells." (PMID 29193730, 2018). "Our results suggest that ADAMTS9 inhibits TGFβ1‐induced AKT activation, which may involve TβR(I/II) in breast cancer cells." (PMID 29193730, 2018). "To ascertain whether the down‐regulation of ADAMTS9 is correlated with promoter hypermethylation, we analysed the methylation status of ADAMTS9 CGI with MSP in eight breast carcinoma cell lines." (PMID 29193730, 2018). "However, the majority of ADAMTS9‐transfected cells were elliptical, suggesting the possibility that ADAMTS9 suppresses epithelial–mesenchymal transition (EMT) in breast cancer cells." (PMID 29193730, 2018). "In cells transfected with ADAMTS9, colony formation was significantly reduced, compared to control cells (reduced to 18% of control in BT549, P < 0.01, and 40% of control in SK‐BR‐3, P < 0.001), suggesting an inhibitory effect of ADAMTS9 on proliferation in breast cancer cells." (PMID 29193730, 2018).
diabetes (7 papers, 2009 to 2025). "The T-allele of rs4607103, near the ADAM metallopeptidase with thrombospondin type 1 motif 9 (ADAMTS9) gene, was associated with an increased risk of diabetes postpartum (OR for the C-allele 0.47 (CI: 0.30–0.73), p = 0.00055; pFDR = 0.039)." (PMID 34801028, 2021). "Another study reported that the diabetes risk allele of ADAMTS9 was associated with impaired beta cell function." (PMID 26218657, 2015). "Risk alleles of all of the 49 investigated T2D loci were associated with incident diabetes with HRs for T2D ≥1, with effect sizes ranging from 1.01 for ADAMTS9 to 1.33 for TCF7L2 per risk allele and p-values <0.05 for 35 of the loci." (PMID 24845081, 2014). "Assuming an additive genetic model the diabetes-associated major C-allele of rs4607103 near ADAMTS9 associated with reduced insulin-stimulated glucose uptake (p = 0.002) during a hyperinsulinemic euglycemic clamp." (PMID 19789630, 2009). "In the same study the diabetes-related C-allele of ADAMTS9 rs4607103 associated weakly with insulin resistance when estimated by homeostasis model assessment of insulin resistance (HOMA-IR)." (PMID 19789630, 2009). "The molecular mechanisms behind the effect of ADAMTS9 on peripheral insulin action and risk of diabetes are unknown." (PMID 19789630, 2009). "However, the molecular mechanisms through which ADAMTS9 affects insulin sensitivity and/or secretion in the diabetes risk variant are unknown." (PMID 26218657, 2015). "Previous studies have also identified numerous genetic loci and gene variants such as FTO, MC4R, ADAMTS9 and GRB14/COBLL1, which have been found to be associated with overweight/obesity and diabetes." (PMID 38089629, 2023). "One study reported that the diabetes risk allele of ADAMTS9 was associated with reduced insulin sensitivity but not with insulin secretion." (PMID 26218657, 2015).